APOE (apolipoprotein E)
Diseases named in the same sentence as APOE in open-access papers (continued):
Sharing a sentence is not in itself a finding about the gene and the disease.
atherosclerosis (continued). "Thus there is an optimal range of plasma apoE levels that is maximally beneficial, and that levels above or below that range impose a risk rather than a benefit for atherosclerosis." (PMID 23537337, 2013). "We aimed to address this apparent discrepancy by investigating the effects of niacin without and with simvastatin on atherosclerosis development and determine the underlying mechanisms, in APOE*3Leiden.CETP mice, a model for familial dysbetalipoproteinemia (FD)." (PMID 23840481, 2013). "ApoE-/- mice are a widely recognized model for hypercholesterolemia that spontaneously develops atherosclerotic lesions, even on a standard chow diet with low fat and no cholesterol and have been used to study the effect of pharmacological or dietary treatments on atherosclerosis development." (PMID 24324736, 2013). "Moreover, endothelial expression of SIRT1 decreases atherosclerosis in apoE null mice." (PMID 23443128, 2012). "However, despite decreased vascular superoxide formation in our apoE−/−/eNOS−/− model, these animals develop increased atherosclerosis, suggesting that the atheroprotective effect of decreased superoxide production does not outweigh the proatherogenic effects of NO deficiency." (PMID 22291917, 2012). "Whether statins play a role in the progression of atherosclerosis was examined in a separate study where apolipoprotein E knockout mice on an atherogenic diet were treated with rosuvastatin (1mg and 10mg/kg of body weight) or pravastatin (10mg/kg of body weight)." (PMID 23369699, 2012). "Taken together with reports of increased arginase activity and expression in atherosclerosis and the decreased NO bioavailability of the hArgII transgenic mice we explored the role of arginase in the development of atherosclerosis in crossed hArgII transgenic mice with apoE −/− mice." (PMID 22829869, 2012). "Therefore, the effect of ginkgolide B was compared with aspirin on atherosclerosis in ApoE−/− mice." (PMID 22662117, 2012). "Experimental studies, in which TGF-ß1 effects have been inhibited in blood vessels of atherosclerosis-prone ApoE (apolipoprotein E) knock-out mice by application of specific antibodies or of recombinant soluble type II receptor resulted in exacerbation of atherosclerosis." (PMID 22829904, 2012). "Bone marrow transfer from C3H/HeJ to ApoE knockouts did not alter atherosclerosis susceptibility." (PMID 21526997, 2011). "The apolipoprotein E knockout (apoE KO) mouse, developed two decades ago, has been used as an experimental model of atherosclerosis because it spontaneously develops hypercholesterolemia and atherosclerosis in a reproducible manner, similar to what is observed in humans." (PMID 21896159, 2011). "Thus the increased production of apoE-rich large HDL particles from differentiated hepatocytes induced by LXR activation might have a role in the protection against atherosclerosis." (PMID 21819577, 2011). "In addition, atherosclerosis is induced or worsened by infection with a number of relevant pathogens (Cytomegalovirus, herpes simplex, Helicobacter pylori, influenza, C. pneumoniae or P. gingivalis) in APOE knockout mice." (PMID 22254144, 2011). "Similarly, others have observed a decrease in NO-dependent vasodilation in atherosclerosis-prone regions, whereas it was preserved in regions that are less prone to atherosclerosis in the descending thoracic aorta of female apoE-/- mice fed a high-cholesterol diet." (PMID 22082357, 2011). "Therefore, the influence of gender on atherosclerosis in the apoE-/- mouse is still under debate." (PMID 22082357, 2011).
atherosclerosis (continued). "Furthermore, we have shown that systemic exposure to diesel exhaust particles or C60 fullerenes by intraperitoneal injection reduced acetylcholine-elicited vasorelaxation in apoE-/- mice with a mild degree of atherosclerosis, whereas opposite effects were seen in wild type mice." (PMID 21054825, 2010). "Furthermore, calorie/dietary restriction or overexpression of SIRT1 in ApoE-/- mice exhibited an anti-atherosclerosis effect by inhibiting oxidized low-density lipoprotein (LDL)-induced apoptosis, upregulation of eNOS expression and improved endothelium-dependent vasorelaxation." (PMID 20663150, 2010). "Therefore, it is not surprising that overexpression of A20, which attenuated both RAGE expression and PKCβII activation in aortic arches of diabetic ApoE-null mice, protected from accelerated atherosclerosis despite persistent hyperglycemia and aggravated dyslipidemia." (PMID 21151899, 2010). "Furthermore, Mclk1 heterozygosity fails to extend lifespan in atherosclerosis-susceptible ApoE-/- mice." (PMID 19416523, 2009). "There are a number of reports where ApoE has been successfully administered via direct gene delivery or virally in a variety of disease models including Alzheimer's disease, hypercholesterolemia, hyperlipidemia, atherosclerosis, experimental stroke and hematopoietic diseases." (PMID 18823563, 2008). "Thus, increased level of gelsolin seen in ApoE+/−-TLR2+/+ mice fed a high fat diet and injected with P. g may be linked to the increased apoptosis and atherosclerosis observed in this group." (PMID 18787704, 2008). "In separate studies, to determine whether effects of PCB-77 would promote cardiovascular diseases linked to obesity, we defined the effects of PCB-77 on the development of obesity, alterations in serum lipids, and atherosclerosis in apolipoprotein E (apoE)−/− mice." (PMID 18560532, 2008). "If indeed the ApoE−/−mouse is a good model for people with atherosclerosis, and if the HR and HRV responses to CAPs in these mice seen in this study are relevant to them, then such responses may be occurring in this human subpopulation at current ambient levels on many days each year." (PMID 16263514, 2005). "Consistent with our data-mining analysis, CD155 and CD274 expression levels were significantly reduced in ApoE−/− aortas, while CD86 levels were increased, supporting the immunosuppressive roles of CD155 and CD274 during atherosclerosis." (PMID 41216502, 2026). "Treatment of apoE knockout mice fed an HFD with diacerein effectively ameliorated liver steatosis/fibrosis and atherosclerosis." (PMID 41811513, 2026). "The paracrine effects of CTRP4 on atherosclerosis were tested by supplementation with CTRP4, either via PVAT transplantation or tail vein injection in CTRP4-/-/ApoE-/- mice." (PMID 41705294, 2026). "We employed an established accelerated atherosclerosis model involving partial ligation of the left renal artery (LRA) and the left common (LCCA), combined with Western diet feeding, in ApoE−/− mice." (PMID 41307849, 2025). "These mice were then crossbred with atherosclerotic-prone ApoE−/− mice and fed a Western-type high-fat diet (HFD) to induce atherosclerosis." (PMID 40349776, 2025). "Our experiments showed that either a 12-week KMUP-1 cotreatment or a 4-week KMUP-1 posttreatment attenuated atherosclerosis lesions and cardiac remodeling in HFD-fed ApoE-KO mice." (PMID 41194853, 2025).
atherosclerosis (continued). "Astragaloside IV, another TCM bioactive, attenuates atherosclerosis via the PI3K/Akt/mTOR pathway activation, reducing oxidative stress and improving lipid metabolism in apoE−/− models, further underscoring the multi-target potential of TCM." (PMID 40872505, 2025). "Hematoxylin‐eosin (H&E) and Oil Red O staining of aortic root sections further confirmed that the severity of atherosclerosis was significantly lower in GRK2ECKO; ApoE‐/‐ mice than in GRK2flox/flox; ApoE‐/‐ mice." (PMID 40492401, 2025). "As seen in ApoE−/− mice, modulating this pathway, QRC reduces the hypochlorous acid (HOCl) levels, which play a toxic role in vascular cells, contributing to atherosclerosis." (PMID 41228388, 2025). "To investigate the critical role of lipid metabolism in atherosclerosis progression and the potential alteration of CD36 in atherosclerosis lesions, we employed a high-fat diet (HFD)-induced ApoE−/− mouse model of atherosclerosis." (PMID 40284439, 2025). "In a recent study, THP-1 macrophages treated with oxidized low-density lipoprotein (ox-LDL) and apolipoprotein E (apoE)−/− mice on a high-fat diet (HFD) were used as vitro and in vivo models, respectively, to investigate the role of GAS5 in atherosclerosis." (PMID 39941145, 2025). "Perinatal exposure to the endocrine-disrupting chemical bisphenol A (BPA) exacerbated atherosclerosis in adult male PXR-humanized and ApoE KO (hPXR•ApoE−/−) mice, because BPA-induced PXR activation epigenetically regulates FA transporter CD36 expression." (PMID 40726484, 2025). "The studies of atherosclerosis and aortic aneurysm in SOSTki.ApoE-/- mice and sost-/-.ApoE-/- mice collectively indicated the cardiovascular protective action of sclerostin." (PMID 41276911, 2025). "Later, they further discovered that Ang II also facilitates both atherosclerosis and AAA formation in apolipoprotein E (ApoE) knockout mice." (PMID 40643529, 2025). "Evidence from 2007 indicated that AKT1 deletion exacerbates atherosclerosis and occlusive CAD, as genetic ablation of AKT1 on an apolipoprotein E knockout background (ApoE(-/-)AKT1(-/-)) led to increased aortic lesion expansion and coronary atherosclerosis." (PMID 40857258, 2025). "As demonstrated by a reduction in aortic atherosclerotic plaques in HHD-fed ApoE mice, lipid levels, and serum TMAO levels, QXXZF significantly mitigated the progression of atherosclerosis." (PMID 40099271, 2025). "A fish oil-rich diet can improve endothelium-dependent vascular relaxation and delay the progression of atherosclerosis by upregulating the expression of MFN2 and OPA1 in aortas of ApoE−/− mice fed with high-fat diet." (PMID 40093324, 2025). "To further substantiate the overlap between human atherosclerosis and mouse atherosclerosis models and the potential involvement of MØ-dependent STAT1-integrative genes we additionally included a bulk RNA-seq data set from HFD fed ApoE knockout mice aorta." (PMID 40607379, 2025). "In vivo findings exposed that endothelial-specific overexpression of TAL1 in ApoE–/– mice significantly impeded the aortic plaque formation, indicating the role of TAL1 in endothelial cells against atherosclerosis." (PMID 40598260, 2025). "To identify the in vivo role and mechanism of ANRIL in atherosclerosis, we developed transgenic mice with the overexpression of ANRIL (full-length NR_003529) and crossed these mice to ApoE−/− mice, resulting in ApoE−/−ANRIL mice." (PMID 40383150, 2025).
atherosclerosis (continued). "Feeding ApoE-/- mice a high-fat diet (HFD) can accelerate the progression of AS, making ApoE-/- mice a widely used model for studying spontaneous atherosclerosis." (PMID 40867523, 2025). "AAV‐MAPK6, ApoE−/−MAPK6flox/floxTEKCre mice and the CXCL12 neutraligand were used to confirm the beneficial effects of MAPK6 against atherosclerosis." (PMID 39763069, 2025). "A 2021 study using ApoE−/− mice and and macrophage-specific conditional LAMP-2A knockout mice revealed that CMA activity is significantly impaired during atherosclerosis progression." (PMID 40244103, 2025). "To further investigate the role of macrophage EP4 in atherosclerosis, we generated myeloid-specific EP4 knockout mice on an ApoE−/− background (ApoE−/− EP4MKO mice)." (PMID 40643540, 2025). "Myeloid-specific human ORP2 overexpression (hORP2MOE) mice were generated and crossed with atherosclerotic-prone ApoE−/− mice and then fed a high-fat diet (HFD) to induce atherosclerosis." (PMID 40349776, 2025). "In fact, as seen in ApoE−/− mice treated with BRB dissolved in drinking water (0.5 g/L), there is an interesting reduction in tissue inflammation and atherosclerosis." (PMID 41228388, 2025). "Changes in the expression of atherosclerosis-related factors, such as reductions in VEGF-C and PDGF-AA and an increase in apolipoprotein E, have also been observed." (PMID 40650247, 2025). "Our results indicate that myeloid-specific hORP2 overexpression significantly reduces the atherosclerotic lesion area in ApoE−/− mice, suggesting a protective effect of ORP2 against atherosclerosis." (PMID 40349776, 2025). "Endothelium‐specific MAPK6 overexpression exerts antiatherosclerotic effects in ApoE−/− mice, elucidating the unexplored role of MAPK6 in atherosclerosis." (PMID 39763069, 2025). "In ApoE−/− mice, overexpression of WWP2 ameliorates atherosclerosis by reducing oxidative stress and inflammation." (PMID 38778460, 2024). "In comparison to ApoE KO mice, PGRN/ApoE DKO mice had more severe atherosclerosis, enhanced levels of adhesion molecules and reduced expression of endothelial eNOS in aortic lesions." (PMID 39558976, 2024). "The absence of BMP4 in PVAT reduces BAT-characteristic gene expressions, increases pro-inflammatory mediators, and exacerbates atherosclerosis plaque formation, while activation of BMP4 signaling reverses these pathological features in ApoE−/− mice." (PMID 38784129, 2024). "Although this is the first report of PVAT involvement in atherosclerosis secondary to CKD+PD, Kawahito64 and colleagues previously showed that PVAT contributes to atherosclerosis in uninephrectomized ApoE−/− mice by activation of the renin‐angiotensin system." (PMID 38979792, 2024). "In summary, our results suggests that exposure of ApoE(−/−) mice to LMDIR regulates monocyte and macrophage responses related to the development of atherosclerosis." (PMID 38816571, 2024). "Moreover, in a hyperglycemic ApoE gene knockout mouse model, liraglutide was found to inhibit atherosclerosis through an AMPK-independent mechanism, suggesting that GLP-1 receptor agonists may exert cardiovascular protective effects through multiple mechanisms." (PMID 39263564, 2024). "In ApoE-/- mice, specific blockade of TGF-β signaling promotes atherosclerosis, as evidenced by increased macrophage activation, reduced collagen, increased plaque size, and increasing instability." (PMID 39399488, 2024).
atherosclerosis (continued). "The following year, they also found that Ang II promotes atherosclerosis development and AAA formation in apolipoprotein E (ApoE) knockout (−/−) mice." (PMID 39247619, 2024). "Apolipoprotein E (APOE), a lipid-transport protein, plays a significant role in the interplay between atherosclerosis and neurodegenerative disorders, notably dementia." (PMID 38831182, 2024). "As an instance, Zhang Y demonstrated that Dingxin Recipe IV mitigated atherosclerosis by adjusting lipid metabolism via the LXR-α/SREBP1 pathway and manipulating the gut microbiota of ApoE−/− mice fed a high-fat diet." (PMID 38952541, 2024). "Ro5-3335 attenuated the progression of established atherosclerosis, as evidenced by a reduction in lesion size compared with that in DMSO-treated ApoE-/- mice." (PMID 39113793, 2024). "Endothelium-specific knockout of DKK1 (DKK1ECKO/APOE-/-) and endothelium-specific overexpression of DKK1 (DKK1ECTg) mice were constructed to investigate the role of endothelial DKK1 in atherosclerosis and SMC-derived foam cell formation in vivo." (PMID 38904030, 2024). "Both were significantly increased by Met in ApoE KO + HFD mice, suggesting that these telomere functions are closely related to the development of atherosclerosis." (PMID 39223261, 2024). "To this end, we constructed a global LXN-deficient mice, and hybridized it with ApoE-/- mice to generate LXN/ApoE double-knockout mice, and then fed HFD for 12 weeks to induce atherosclerosis." (PMID 39424784, 2024). "In this study, we found that apoE KO rabbits, a model of type III hyperlipoproteinemia, showed more severe atherosclerosis in the aorta and femoral artery." (PMID 39087075, 2024). "The ApoE−/− mice which treated by K/BxN serum and HFD were successfully simulated arthritis combined with atherosclerosis and developed severe, destructive arthropathy." (PMID 39716053, 2024). "The E3 ligase TRIM7 promotes the proliferation and migration of VSMCs in atherosclerosis, and the downregulation of TRIM7 alleviates atherosclerosis in ApoE−/− mice." (PMID 38778460, 2024). "To anti-atherosclerosis activity, flaxseed oil lessened the number of Eubacterium and Firmicutes/Bacteroidetes ratio at the phylum level in TMAO and high-fat diet-induced ApoE−/− mice." (PMID 39403395, 2024). "APOE*3-Leiden.CETP mice were also employed to demonstrate the efficacy of anti-PCSK9 therapies for lowering LDL-C and TGs, which translated to reduced atherosclerosis development in the aortic root." (PMID 39404395, 2024). "The APOE*3-Leiden.CETP model is characterized by substantial genetic overlap with human NASH and atherosclerosis." (PMID 39404395, 2024). "Both Pdgfd KO and control (Pdgfd+/+, Myh11CreERT2, ROSAtdT/+, ApoE−/−, designated as Ctl) mice were administrated tamoxifen at the age of 8 weeks, followed by high-fat diet (HFD) feeding for 16 weeks to induce atherosclerosis." (PMID 36792607, 2023). "To determine the role of B cell TNIK in atherosclerosis, we generated ApoE−/−TNIKfl/fl (TNIKBWT) and ApoE−/−TNIKfl/fl CD19-cre (TNIKBKO) mice, which were fed a high cholesterol diet for 10 weeks." (PMID 37215541, 2023). "However, T-cells from Apolipoprotein e deficient (Apoe−/−) mice with advanced atherosclerosis due to 20 weeks of cholesterol-rich Western-type diet (WTD) feeding, show decreased T-cell proliferation and increased T-cell apoptosis compared to T-cells from Apoe−/− mice fed a chow diet [25•]." (PMID 37395922, 2023).